CD28 (CD28 molecule)
Diseases named in the same sentence as CD28 in open-access papers (continued):
Sharing a sentence is not in itself a finding about the gene and the disease.
autoimmune thyroiditis (3 papers, 2012 to 2020). "Our results on CD28 expression differ from a study in 35 children with autoimmune thyroiditis in whom baseline CD28 expression was similar to healthy controls." (PMID 24006909, 2013). "However, after unspecific stimulation in vitro, CD28 expression decreased in autoimmune thyroiditis patients to a much higher extend as seen in controls in that study, which may underline the characteristic down-regulation of CD28 seen in HT patients." (PMID 24006909, 2013).
bladder cancer (3 papers, 2021 to 2025). "In bladder cancer, TRMs can be activated by anti-CD3, anti-CD28, and IL-15 stimulation, leading to proliferation and increased T-bet, perforin, and granzyme B expression, particularly in the PD-1+ subset." (PMID 41479900, 2025). "Specifically, the AC of HLA DR+CD8br, CD28 on CD28+CD45RA+CD8br T cell and DN AC may offer protective effects against bladder cancer." (PMID 39450166, 2024).
brain ischemia (3 papers, 2015 to 2023). Diminished or absent blood supply to the brain caused by obstruction (thrombosis or embolism) of an artery resulting in neurologic damage. "For instance, HMF showed neuroprotection against brain ischemia by inducing BDNF production and anti-inflammatory actions and demonstrated an immunomodulatory function for the reduction of interleukin-4 expression in CD3/CD28-stimulated spleen cells in mice." (PMID 37180721, 2023).
Chronic colitis (3 papers, 2016 to 2021). A chronic inflammatory disease of the large intestine (colon, cecum and rectum). "The level of IL-17A with anti-CD3 and anti-CD28 mAb stimulation was noticeably reduced in the IL-33-treated chronic colitis group compared with the control group, while a similar concentration of IL-17A without any stimulation was observed in these two groups." (PMID 30539029, 2018). "Studies have shown that improvements following LcS treatment on DSS-induced chronic colitis were associated with a decrease in IFN-γ production and an increase in IL-4 production in LI-LPMC, when stimulated with CD3ε/CD28." (PMID 27500935, 2016). "The level of IFN-γ with anti-CD3 and anti-CD28 mAb stimulation and without any stimulation was strikingly reduced in the IL-33-treated chronic colitis group compared with the control group." (PMID 30539029, 2018). "The level of IL-10 with anti-CD3 and anti-CD28 mAb stimulation and without any stimulation was significantly increased in the IL-33-treated chronic colitis group compared with the control group." (PMID 30539029, 2018). "The level of IL-4 and IL-5 with anti-CD3 and anti-CD28 mAb stimulation and without any stimulation was markedly increased in the IL-33-treated chronic colitis group compared with the control group." (PMID 30539029, 2018). "The level of IL-13 was noticeably increased with anti-CD3 and anti-CD28 mAb stimulation, and similar results were observed without any stimulation in the supernatants of the MLN of the IL-33-treated chronic colitis group compared with the control group." (PMID 30539029, 2018). "Regardless of whether there was anti-CD3/CD28 antibody stimulation, IFN-γ, IL-17A, and IL-21 were significantly decreased (P < 0.05), and IL-10 was significantly increased in the chronic colitis + Se-enriched L. acidophilus group compared with the chronic colitis group (P < 0.05)." (PMID 34532332, 2021).
Cirrhosis (3 papers, 2017 to 2021). A chronic disorder of the liver in which liver tissue becomes scarred and is partially replaced by regenerative nodules and fibrotic tissue resulting in loss of liver function. "Others have reported evidence of immunosenescence (i.e., lower CD8 + CD28+ T-cell proportions) among HIV uninfected people with cirrhosis who consumed > 90 g/day of ethanol in prior 5 years compared to healthy controls consuming 10-15 g/day ethanol." (PMID 31892306, 2019).
depression (3 papers, 2016 to 2022). "Our final results were BMI, fatigue, depression, unstable emotions, and the proportion of CD27+CD28+ Th/Treg, CD27−CD28− Th/Treg, CD45RA−CD27− Th, and CD45RA+HLADR+ Th cells." (PMID 34955935, 2021). "At the same time, the percentages of IL-10-producing and FoxP3-expressing CD4+ T-cells (with CD3/CD28-stimulation) was higher in MS patients without depression." (PMID 36189272, 2022). "BMI, fatigue, depression, unstable emotions, and CD27+CD28+ Th/Treg, CD27−CD28−Th/Treg, CD45RA−CD27− Th, and CD45RA+HLADR+ Th cells may be important characteristics of the differences." (PMID 34955935, 2021).
dermatitis (3 papers, 2018 to 2024). An inflammatory process affecting the skin. "Remarkably, mice that received Dsg3H1-pTh17 cells and were treated with abatacept showed nearly complete prevention of skin lesions, indicating the critical role of CD28 signaling in skin inflammation." (PMID 38226171, 2024). "We demonstrated that CD28 blockade selectively inhibits effector Th17 cells that are highly differentiated, leading to the complete inhibition of dermatitis." (PMID 38226171, 2024). "To confirm this hypothesis, we used the Dynabeads® Human T-Activator CD3/CD28 kit to activate and expand the T cells of the dermatitis patient PBMCs." (PMID 30297858, 2018). "Dermatitis patient specimens also showed increased PpIX levels in addition to artificially-activated normal PBMCs after CD3/CD28 stimulation, suggesting that the PpIX increasing phenomenon may be common in activated cells." (PMID 30297858, 2018). "When these LN cells were stimulated by anti-CD3 with or without anti-CD28 antibody (Ab), more IL-17A was secreted by LN cells of CD4CreTTPf/f mice than that of WT mice, suggesting a correlation between IL-17 and the development of dermatitis in the aging CD4CreTTPf/f mice." (PMID 32922402, 2020).
endometriosis (3 papers, 2021 to 2023). The growth of functional endometrial tissue in anatomic sites outside the uterine body. "It was found that the expression of CD28+ was higher in the women with endometriosis after being stimulated with IL-2." (PMID 36313261, 2022). "The concentration of CD3+CD28+ (co-stimulatory) was significantly lower in the endometriosis group (65.62 ± 5.38) compared to in its counterpart (50.24 ± 4.22) (p = 0.04) before stimulation." (PMID 36313261, 2022). "Increased expression of CD160 and decreased CD28 play a role in inhibiting NK cell activation and T cell response in women with endometriosis." (PMID 36313261, 2022). "In this study, we found that the expression of CD3+CD28+ was significantly lower in the peripheral blood of women with endometriosis than in the control group women." (PMID 36313261, 2022). "The concentration of CD3+CD28+ (co-stimulatory) was significantly lower in the endometriosis group (50.24 ± 4.22) compared to in its counterpart (65.62 ± 5.38) (p = 0.04) before stimulation." (PMID 36313261, 2022). "However, a higher frequency of CD8+CD28- (T suppressor cells) was observed in the women with endometriosis." (PMID 36313261, 2022). "In conclusion, this study, combined with a previous one, demonstrated that the increased expression of CD160 and decreased expression of CD28 may play a role in inhibiting NK cell activation and T cell response in endometriosis." (PMID 36313261, 2022). "The results of the present study show for the first time that PF from women with advanced endometriosis displays immunomodulatory activity toward both unstimulated and CD3/CD28/IL-2-stimulated CD4+ T cells." (PMID 34360900, 2021). "To see whether the PF from the patients with endometriosis and the control subjects may affect in vitro generation of Treg and Th17 cells we evaluated specific phenotype changes of the unstimulated and CD3/CD28/IL-2-stimulated CD4+ T cells following their 5-day culture." (PMID 34360900, 2021).
eosinophilia (3 papers, 2017 to 2025). "When analyzing the T-cells population, CD28 expression is increased in spleen and MHC-II upregulated in bone marrow upon T. canis infection, indicating productive activation of this subset during peak eosinophilia." (PMID 29445372, 2018).
esophageal cancer (3 papers, 2016 to 2026). A primary or metastatic malignant neoplasm involving the esophagus. "The CD3 on CD28+ CD45RA− CD8br has been shown to have a significant causal relationship with esophageal cancer, although its mechanism in thymoma remains largely unexplored." (PMID 41497137, 2026).
leprosy (3 papers, 2014 to 2022). Leprosy is a chronic infectious disease affecting primarily the skin and peripheral nervous system. "Anti-CD28/CD49d were used in all the culture of mononuclear cells as costimulatory molecules and to test whether Tregs influence development of leprosy reactions, we analyzed CD4+ and CD8+ Treg cells, defined as CD25+Foxp3+, in multibacillary patients, T1R, T2R and HV." (PMID 35924037, 2022).
liver cancer (3 papers, 2019 to 2024). An epithelial or non-epithelial malignant neoplasm that arises from the liver. "We found that CD14, CD25, and CD28 can also be expressed by liver cancer cells, but their roles need to be further explored." (PMID 31523179, 2019). "Our project has proved that autologous infusion of red blood cell surface membrane proteins CD28 and MHC combined with CD8+ T cells can promote the proliferation of CD8+ T cells to inhibit the malignant transformation of liver cancer." (PMID 36213824, 2022). "In summary, our project has successfully proved through a series of experiments that autologous infusion of red blood cell surface membrane proteins CD28 and MHC combined with CD8+ T cells can promote the proliferation of CD8+ T cells to inhibit the malignant transformation of liver cancer." (PMID 36213824, 2022). "Thus, we evaluated the influence of MRC-5-CM on expression of TLRs and leukocyte-differentiation antigens (CD14, CD25, CD28, and CD61) in liver cancer cells." (PMID 31523179, 2019).
metabolic syndrome (3 papers, 2015 to 2025). A cluster of metabolic risk factors for CARDIOVASCULAR DISEASES and TYPE 2 DIABETES MELLITUS. "VAT and metabolic syndrome were associated with higher KLRG1 expression in CD28+ and CD28− cells." (PMID 26611787, 2015). "The proportion of CD8+CD28− and CD8+PD1+ T cells was positively associated with dyslipidemia, while CD8+CD28+PD1− T cells were inversely associated." (PMID 40136325, 2025). "Peripheral CD28−/CD8+ and PD1+/CD8+ T cell proportions were significantly associated with several high-risk factors, including deep myometrial invasion, and LVSI, as well as metabolic disorders such as dyslipidemia." (PMID 40136325, 2025).
mild cognitive impairment (3 papers, 2020 to 2022). "Senescent CD28- T cells may be also implicated in modulating cognitive processes, as expansion of this subset has been associated with cognitive impairment in RA." (PMID 32190092, 2020).
osteoporosis (3 papers, 2017 to 2021). A condition of reduced bone mass, with decreased cortical thickness and a decrease in the number and size of the trabeculae of cancellous bone (but normal chemical composition), resulting in increased fracture incidence. "Our data indicate that senescent T-cells promote osteoclastogenesis more efficiently than conventional CD28+ T-cells, which might contribute to the pathogenesis of systemic bone loss in RA and primary osteoporosis." (PMID 29472917, 2018). "Apart from that, CD4+CD28- T cells have also been reported in HIV-infected individuals and lupus erythematosus-affected patients, in which their activity could explain the increased risk of developing osteoporosis observed in these diseases." (PMID 34341698, 2021). "During osteoporosis, CD4+CD28- T lymphocytes expressed higher levels of TNF-α and intensely induced the activation of TRAP in osteoclasts as compared with CD4+CD28+ T lymphocytes." (PMID 34341698, 2021). "We demonstrated here the lower level of plasmacytoid DCs in women with osteoporosis and CD3+CD28+ T-lymphocytes in women with osteopenia." (PMID 28696349, 2017).
ovarian tumor (3 papers, 2017 to 2021). "In this preclinical study, we investigated the efficacy of using anti-CD3/anti-CD28 magnetic beads and IL-2 to expand TILs from freshly resected ovarian tumours." (PMID 30039427, 2018). "Using anti-CD3/anti-CD28 Dynabeads and high-dose IL-2, TILs were expanded from 89.7% of surgically resected ovarian tumours." (PMID 30039427, 2018). "In an ovarian tumor (SK-OV3) mouse model, CD3/CD28 Dynabead 4D5-BBZ CART cells showed faster tumor control than OKT3-28BB-86BBL RNA-T 4D5-BBZ CAR T cells." (PMID 28523432, 2017).
psoriatic arthritis (3 papers, 2021 to 2024). Joint inflammation associated with psoriasis. "The simultaneous inhibition of ICOS and CD28 signaling, achieved through the use of inhibitors like Acazicolcept, has proven effective in reducing inflammation and slowing the progression of RA and psoriatic arthritis (PsA)." (PMID 38041172, 2023).
pulmonary TB (3 papers, 2010 to 2023). "As per our knowledge ours is the first study where differential modulation of TCR or TCR/CD28 induced downstream signalling events like MAPKs in the PBMCs of pulmonary TB patients has been observed." (PMID 26552486, 2015). "We also noticed curtailment of binding activity of NFAT in anti CD3+CD28 stimulated cells in pulmonary TB patients after treatment with ESAT-6, PPD and H37Rv." (PMID 26552486, 2015). "However, in pulmonary TB patients significant inhibition of TCR/CD28 triggered ERK1/2 phosphorylation by Ag85A and ESAT-6 was observed." (PMID 26552486, 2015). "Our study identified unique gene signatures (IL-27, STAT1, IRF1, TLR4, IL-15, IL-2RA, IL-24, TGFβ, CD28, CD80, NFATC1, and PTGDR2) that discriminate active pulmonary TB from uninfected controls using unstimulated PBMCs." (PMID 37460564, 2023). "Here, we investigated effect of M. tuberculosis antigens Ag85A and ESAT-6 on T cell signalling events in CD3/CD28 induced Peripheral blood mononuclear cells (PBMCs) of PPD+ve healthy individuals and pulmonary TB patients." (PMID 26552486, 2015). "We also noted that Ag85A, ESAT-6, PPD and H37Rv curtailed TCR/CD28 induced binding activity of NFAT on IL-2 promoter in PPD+ve healthy individuals and pulmonary TB patients both." (PMID 26552486, 2015). "We did not observe any effect on p38 phosphorylation in TCR/CD28 induced cells of healthy individual after treatment with M. tuberculosis antigen whereas in pulmonary TB patients Ag85A and ESAT-6 significantly curtailed p38 phosphorylation." (PMID 26552486, 2015). "Interestingly, we observed that ESAT-6 significantly curtailed TCR/CD28 induced phosphorylation of ERK1/2 in healthy individuals and pulmonary TB patients both." (PMID 26552486, 2015).
relapsing remitting MS (3 papers, 2016 to 2022). "(2017) found that production of Th17-cytokines IL-17, IL-22, and GM-CSF by anti-CD3/CD28-activated PBMCs is higher in relapsing-remitting MS patients with fatigue (n=15) compared to MS patients without fatigue (n=15)." (PMID 36189272, 2022). "For instance, we have recently evidenced that CD28-mediated upregulation of pro-inflammatory cytokines (i.e., IL-8, IL-6, IL-21, and IL-17A) was higher in human primary T lymphocytes from relapsing-remitting multiple sclerosis patients (RRMS) compared with HD." (PMID 28491063, 2017). "(2021) showed the inhibitory effect of fluoxetine on IL-17, IFN-γ, and GM-CSF production by anti-CD3/CD28-activated CD4+ T-cells in patients with relapsing-remitting MS and healthy subjects, which confirms the anti-inflammatory effect of fluoxetine on Th17-cells in MS." (PMID 36189272, 2022).
schizophrenia (3 papers, 2017 to 2024). A major psychotic disorder characterized by abnormalities in the perception or expression of reality. "In addition, decreased expression of CD28 on T-cells is a key indicator of T-cell aging, eventually resulting in immune incompetence, whereas a CD28 SNP rs3116496 may be associated with schizophrenia risk, especially in deficit patients." (PMID 38532012, 2024). "Single nucleotide polymorphisms have been analysed in many cytokines, in particular, those that are associated with altered levels in schizophrenia such as TNF-α, IL1-β, IL-6, IL-10, INF-γ, and in the genes encoding the immune system regulatory proteins CTLA-4 and CD28." (PMID 29317797, 2017).
Sézary syndrome (3 papers, 2015 to 2023). "Furthermore, in Sézary syndrome patients, the fusion of the transmembrane and extracellular domains of CTLA-4 with the intracytoplasmic domain of CD28 has been reported, which results in upregulation in CD28 signaling." (PMID 37746258, 2023).
T-cell acute lymphoblastic leukemia (3 papers, 2019 to 2021). Acute lymphoblastic leukemia of T-cell origin. "HSH2D inhibits the transcriptional activation of the IL-2 promoter, specifically at the RE/AP element of IL-2, which is regulated by CD28, and HSH2D expression contributes to methotrexate resistance in human T-cell acute lymphoblastic leukemia." (PMID 34512722, 2021). "The uninfected cells that were tested included the acute T-cell lymphoblastic leukemia cell lines, Jurkat and CEM, as well as resting and anti-CD3/anti-CD28-activated primary CD4+ T-cells." (PMID 31251786, 2019).
thyroid cancer (3 papers, 2021 to 2025). "To find out the optimal co-stimulatory domain for thyroid cancer treatment, we compared the in vitro anti-tumor functions of CD28 and 4-1BB-based TSHR CAR-T cells." (PMID 35252208, 2022). "Overall, we observed significant association between IGSF10 and immune checkpoint genes such as CD200R1, VSIR, CD160, CD28, BTLA, and CD40LG in several tumors including low-grade glioma (LGG) and thyroid carcinoma (THCA)." (PMID 34351868, 2021). "Our research findings strongly demonstrate that many immune properties against thyroid cancer exist in Treg, such as CD28‐ DN (CD4‐ CD8‐) %DN, CD3 on activated and secreting Treg, CD3 on CD28+ CD4+, CD28 on CD39+ CD4+, CD127 on CD45RA‐ CD4 not Treg and CD4 on secreting Treg." (PMID 41189243, 2025).
triple-negative breast carcinoma (3 papers, 2024 to 2025). An invasive breast carcinoma which is negative for expression of estrogen receptor (ER), progesterone receptor (PR), and human epidermal growth factor receptor 2 (HER2). "CAR T cells were activated using CD3+CD28-coated beads or co-culture with (MUC1+ ErbB+) MDA-MB-468 triple-negative breast cancer (TNBC) cells, making comparison with unstimulated controls." (PMID 38745414, 2024).
Wegener’s Granulomatosis (3 papers, 2017 to 2021). "Over the years, CD4+CD28− T cells have been shown to be implicated in various inflammatory conditions including granulomatosis with polyangiitis (GPA), where CD4+CD28− T cells were linked to increased infection and mortality." (PMID 28303136, 2017).
abortion (2 papers, 2020 to 2024). the ending of pregnancy by removing a fetus or embryo before it can survive outside the uterus. "In Treg cells, Resting Treg % CD4 Treg, Resting Treg %CD4, CD28-CD127-CD25 ++ CD8br %T cell and CD127 on CD28+ CD45RA+ CD8br were positively associated with abortion (OR > 1)." (PMID 39388432, 2024). "However, a retrospective study analyzed a polymorphism of CD28 and concluded that the SNP of CD28 in recurrent spontaneous abortion (RSA) patients was distinct from that in normal pregnant women." (PMID 32265918, 2020). "CD3 on activated & secreting Treg, CD4 on CD28+ CD4+ and CD4 on resting Treg were negatively associated with abortion (OR < 1)." (PMID 39388432, 2024).
acute GVHD (2 papers, 2015 to 2022). "We compared the IL-6 responsiveness for patients with and without previous acute GVHD when anti-CD3+anti-CD28 was present during IL-6 stimulation." (PMID 35566660, 2022).